CD40 (CD40 molecule)
Diseases named in the same sentence as CD40 in open-access papers (continued):
Sharing a sentence is not in itself a finding about the gene and the disease.
tumor (continued). "Equally important is the notion that reducing or inhibiting CD40 signaling on macrophages would not induce new problems, such as heightened tumor growth (induced by increased angiogenesis) or immune-suppression (by not interfering in the adaptive immune system)." (PMID 27146510, 2016). "Because anti-CD40 treatment increased CD8+ T cell infiltration and also upregulation of PD-1 and PD-L1, we tested the hypothesis that a combination of αCD40 and αPD-L1 would induce systemic anti-tumour immunity in this model." (PMID 26918344, 2016). "We hypothesized that harnessing MWNT for concurrent delivery of cytosine−phosphate−guanine oligodeoxynucleotide (CpG) and anti-CD40 Ig (αCD40), as immunoadjuvants, along with the model antigen ovalbumin (OVA) could potentiate immune response induced against OVA−expressing tumour cells." (PMID 27475727, 2016). "Also, T cell function was inhibited when chemotherapy with CpG-ODN and anti-CD40 were administered without supplemental tumor antigen." (PMID 26082836, 2015). "Later reports revealed that the expression of CD40 was not restricted to B cells but that it was also expressed on monocytes, dendriticcell, and on non-hematopoietic cells including keratinocytes, fibroblasts, neurons, endothelial, epithelial, and tumor cells." (PMID 24885116, 2014). "Additionally, CD40 mutant expression was not correlated with sex, age, tumor size, or pathological differentiation (P >0.05)." (PMID 24885116, 2014). "One study demonstrated that administration of anti-CD40 Ab to tumor-bearing animals leads to maturation of DC capable of stimulating T cell activation, suggesting that the tumor either fails to support DC maturation or that suppression of DC maturation by the tumor is a reversible process." (PMID 23874338, 2013). "Interestingly, CD40 is also expressed in the membrane and cytoplasm of tumour cells but is absent from non-proliferating tissues." (PMID 23125850, 2012). "We aimed to enhance the effect of tumor lysate with regard to induction of DC maturation, but as reported by others we had to face the problem that the tumor lysate rather did not induce DC maturation, in terms of upregulation of surface markers CD40, CD80, and CD86." (PMID 21615909, 2011). "Negative expression of CD40 was observed in normal tissues (from around the tumours)." (PMID 19865524, 2009). "The clinicopathological factors, including age, sex, tumor size, gross appearance, degree of cellular differentiation, histological classification, depth of tumor invasion, lymph node metastasis, peritoneal dissemination, and TNM stage were analyzed according to the different expression of CD40." (PMID 19865524, 2009). "CD40 expression is a common feature of haematopoietic and nonhaematopoietic tumours." (PMID 12771917, 2003). "Moreover, TNF-α and IFN-γ could induce high levels of CD40 on mature MDSCs through interacting with CD40L on T cells after CTT to promote Th1-dominant CD4+ T cell differentiation and orchestrate CTT-induced long-term anti-tumor immunity." (PMID 38791188, 2024). "Given the increase in tumor antigen-specific CD8+ T cells driven by CTLA4i, together with the increased expression of PD1 by lung CD4+ and CD8+ T cells driven by anti-CD40 we reasoned that anti-PD1 could be necessary to sustain responses elicited by RT+CTLA4i+anti-CD40." (PMID 37620372, 2023). "However, CD40 may not have significant anticancer efficacy as a single treatment in patients with immunologically “cold” tumor." (PMID 36523993, 2022). "Finally, it should be noted that HRS cells are subjected to a multitude of strong NF-κB-activating signals from the tumour microenvironment that support their growth and survival, including activation through CD40, which induces both the canonical and non-canonical NF-κB pathways." (PMID 36289712, 2022).
tumor (continued). "The next target is CD40, a costimulatory molecule, member of the tumor-necrosis factor receptor family that is expressed on the surface of immune cells (B cells, dendritic cells, and macrophages), non-immune cells (endothelial and epithelial cells), and on tumor cells." (PMID 35214076, 2022). "Interestingly, it was shown that the tumor-derived cytokines are able to activate the p38 MAPK pathway and STAT3 signaling in DCs, leading to lower expression levels of costimulatory molecules (i.e., CD40, CD80), activation markers (e.g., HLA-DR) and CD1a, and functionally abnormal DCs." (PMID 35965494, 2022). "It was found that the risk score had negative correlation with the BTLA, CD27, CD40, CD80, and TNFRSF14 expression, which had significant differences in different risk groups, indicating that tumor immunosuppression might lead to an increased risk score of patients." (PMID 34899848, 2021). "Finally, evidence to date suggests that CD40+ DC activation is a critical and nonredundant mechanism to convert “cold” tumors (i.e., lacking a T cell tumor infiltrate) into “hot” ones (i.e., having a prominent T cell tumor infiltrate), sensitizing them to checkpoint inhibition therapy." (PMID 34073720, 2021). "CD40 ligation provides essential activation signals for immune cells, although its function in the promotion or inhibition of tumorigenesis and progression via regulation of TNF alpha (TNFα)‐induced apoptosis, angiogenesis, tumor cell migration and invasion, and chemoresistance is unknown." (PMID 34184409, 2021). "Therefore, combining RT with IO or immune-stimulatory agents which act to reprogramme myeloid cells and drive increased T cell infiltration into tumours (e.g., TLR agonists, anti-CD40 mAb, anti-OX40 mAb) may be required to overcome this immunosuppressive TME and improve tumour control and survival." (PMID 33008040, 2020). "Interestingly, a combination of anti-CD40 agonist and inhibition of CSF-1R induced macrophage pro-inflammatory phenotype prior CSF-1R mediated elimination, which was sufficient to reinvigorate CD8+ T cell response in transplanted tumours that were either resistant or sensitive to ICBs." (PMID 31331034, 2019). "In conclusion, we have generated bispecific agonist CD40/FAP DARPin® molecules able to activate the CD40 pathway in cellular assays in a targeting-dependent manner, supporting the hypothesis that these DARPin® molecules could lead to a tumor-localized immune activation in vivo." (PMID 30400822, 2018). "Therefore, we proceeded to in vivo experiments, where we activated isolated B lymphocytes with agonist anti-CD40 antibody, washed the cells thoroughly, mixed them with isolated T cells and immediately transferred all cells to RAG1-/- mice, previously injected with TC-1 tumor cells." (PMID 29975708, 2018). "Combining local imiquimod with anti-CD40 therapy reinforced the local response, and upregulated the ratio of regression of distal tumor found that imiquimod inhibited the growth of cutaneous breast cancer cells by a CD8 dependent mechanism, but did not cause complete tumor regression." (PMID 28620298, 2017). "In a murine 4T1 model of breast cancer syngeneic to Balb/c mice, we reported that the transfer of LPS/anti-CD40- activated 4T1 TDLN B cells significantly reduced the induction of spontaneous 4T1 pulmonary metastases, and these effector B cells could directly kill 4T1 tumor cells." (PMID 27528023, 2016). "Furthermore, the expression of all well-established costimulatory molecules, including CD40, CD54, CD80, CD83, CD86, 4-1BB, GITR (glucocorticoid-induced TNFR-related protein), OX40L, and SLAM (signaling lymphocytic activation molecule), was downregulated in DC-tumor fusion cells." (PMID 26605345, 2015). "However, it is not known whether tumor-derived immunosuppressive factors affect the antigen-presenting capacity of CD40-activated B cells in a similar fashion as in DC." (PMID 22592077, 2012).
tumor (continued). "However, it has been reported that Treg from tumor-bearing mice may impair the expression of DC costimulatory molecules CD80, CD86, and CD40, suppress DC production of proinflammatory cytokines IL-12 and TNF-α, and inhibit their ability to induce T-cell activation in vitro." (PMID 22110524, 2011). "Therefore, the immune profile captured in an earlier biopsy may not fully represent the tumor contexture, which could lead to misclassification, where a tumor initially low in CD40 expression might evolve to become a high-expressing tumor at a later stage, or vice versa." (PMID 41182434, 2025). "In the tumor-draining lymph nodes, we observed that adding chemotherapy to innate agonists significantly increased the infiltration of CD86 + mature DCs, but not CD40 + DCs." (PMID 39871312, 2025). "FcγR-independent authentic CD40 agonists, as described in this study, however, are not useful when CD40 targeting is envisaged with the intention to stimulate FcγR functions, such as ADCC, ADCP, and CDC to kill tumor cells with high CD40 expression levels." (PMID 38214443, 2024). "Remarkably, unlike Nano/TM and Nano/CD40, DiR-loaded Nano/CLDN18.2 and NanoBE exhibited enhanced tumor accumulation and prolonged retention over time (circle)." (PMID 38468289, 2024). "CD31 acts as a co-inhibitory receptor, where CD31+ DCs are more tolerogenic, suggesting in the absence of FGL2 cDC2s in B16F10 tumours are more activated (MHCII+, CD86+, CD40+) and less immunosuppressive (CD31+)." (PMID 38191799, 2024). "Those samples were then tested on HEK-Blue CD40L cells that express a reporter phosphatase under the control of a CD40 inducible promoter and in the presence or absence of PDL1-expressing tumor cells (i.e., Hs746T)." (PMID 38053848, 2023). "Monocyte/macrophages within the 4-culture tumor spheroids were characterized by a higher expression of CD163, CD206, PD-L1, and CD40 than those in the non-cancerous spheroids suggesting their differentiation towards an immunosuppressive phenotype." (PMID 37519820, 2023). "Although the number of converted tumor-migratory CD103+ DCs and CD11b+ did not change in either group, there was an increased proportion of both DC subsets co-expressing CD40 and CD80 in the radiation-treated Moc1 group." (PMID 35487695, 2022). "Instead, we confirm that CD40 and CD3 ligation are required in the tumor rather than the dLN using FTY720 and by spatially separating the CD40L and CD3 signals in the tumor." (PMID 36073543, 2022). "Although Moc2 is a poorly radioimmunogenic tumor, Moc2 tumors exhibited an increase in CD103+ DC but not CD11b+ DC co-expressing CD40 and CD80 in the TdLN after radiation therapy." (PMID 35487695, 2022). "Both CD40-positive and CD40-negative B cells were isolated from tumors of TLR-7/8 agonist-treated wild-type mice and adoptively transferred into tumor-bearing B cell KO mice, which were treated with anti-PD-L1 and TLR-7/8 agonist." (PMID 35720386, 2022). "None of the treatments had any effect on CD40, CD80, or CD86 expression on DCs isolated from the tumor while the combination treatment significantly increased the MHC I antigen presentation on these cells." (PMID 36551577, 2022). "All the treatments including OVA resulted in expressions of CD40 and CD80 but not CD86 in tumor-derived macrophages." (PMID 36551577, 2022). "We observed that ~ 91.3% of the RGS-induced CD40+CD45− cells did not express tdTomato (tdTomato−), suggesting that they were tumor cells that were injected into mice to generate tumors rather than the endogenous stromal cells from ROSA mice." (PMID 34092233, 2021). "The mouse version of MSLN × CD40 activated B cells and monocyte-derived DCs and showed MSLN-dependent antitumor efficacy without liver toxicity in syngeneic tumor models." (PMID 34358141, 2021).
tumor (continued). "As such, anti-IL-6 monotherapy fails to induce a robust anti-tumor activity and to overcome GBM resistance to checkpoint blockade, likely due to reduced co-stimulatory CD40 signal and insufficient T-cell infiltration and activation." (PMID 34103524, 2021). "In absence of TLR stimulation, circulating and tumor‐infiltrating 20 h‐cultured cDC2s and pDCs displayed higher levels of CD80, CD40 and/or CD86 (% and/or MFI) when compared to HD." (PMID 33282290, 2020). "Positive correlations between CD40‐expressing DC subsets were lost in patients, and negative correlations between CD80‐expressing DCs and CD86+ pDCs emerged in tumor infiltrates, which fits with impacts observed on clinical outcomes." (PMID 33282290, 2020). "CD40 is a TNF receptor superfamily member expressed on APCs, including DCs, B cells and monocytes, as well as by many other non-immune and tumor cells." (PMID 32150821, 2020). "Secreted factors from OAC tumour biopsies can significantly reduce CD83 expression on dendritic cells but not the expression of PD-L1, CD40, HLA-DR and CD54." (PMID 32694701, 2020). "Notably, the expression levels of CD80 and CD40 on pDCs in tumor sites decreased in the shRNA-treated group, whereas the activation of pDCs in spleen was not impaired, suggesting that shRNA-induced tumor apoptosis might suppress the activation of pDCs." (PMID 31849942, 2019). "Our results demonstrated that the expression of CD40, CD80, CD86, and HLA-DR was downregulated after coculture with H-1299 tumor cells compared with that on CD1c+ DCs that were not incubated with H-1299 cells." (PMID 31921114, 2019). "Indeed, anti-CD40 treated DCs isolated from donors with TC-1 tumors could not inhibit tumor growth in RAG1-/- mice when transplanted with T cells, differently from what we observed with the B lymphocytes, which suggested that these cells were more resistant to the effects of the tumor." (PMID 29975708, 2018). "IL-2/anti-CD40 immunotherapy alone did not significantly improve CTL activity in DLN, spleen or tumor of elderly mice." (PMID 30459812, 2018). "By contrast, treatment of KPC mice with CD40 agonist (FGK45) and gemcitabine transiently blocked PDAC development through re-education of tumor-infiltrating macrophages and stromal remodeling, but was not able to invoke an adaptive antitumor immune response." (PMID 30158932, 2018). "CD40 and CD86 expression were comparable in DCs from tumour-bearing mice regardless of Y27632 treatment." (PMID 29867097, 2018). "As a control for B cell independent effects of anti-CD40, a second group of SWHEL-negative Rag2−/− littermates was inoculated with tumor but did not receive anti-CD40." (PMID 27121060, 2016). "It was also demonstrated that intratumoral administration of anti-CD40 antibodies was effective in licensing strong systemic CTL immunity, resulting in eradication of distant tumor nodules without side effects." (PMID 25682197, 2015). "Both immunostimulatory CD8α + and CD8α- DC subsets were increased, whereas expression of activation markers CD40, CD70, CD86, and of MHC Class I molecules in either subsets of tumor infiltrating DCs were not altered by CD1d blockade." (PMID 25349699, 2014). "Mouse bone-marrow-derived DCs first activated with the TLR4 ligand LPS and exposed to tumor-induced Treg maintain expression of CD80, CD86, and CD40, produce IL-12 or TNF-a, and are not impaired in their allostimulatory activity." (PMID 22110524, 2011). "The immaturity of CD1a+ DCs within the tumour tissue was further demonstrated by the absence of maturity markers, such as DC-LAMP, CD40, or RelB expression, as assessed by serial analyses in confocal microscopy of double fluorescence-stained sections." (PMID 20969772, 2010). "The ligation of CD40 expressed by cDC1 during CD4+ T‐cell priming is critical for robust licensing of cDC1s; without this interaction, tumor rejection mediated by CD8+ T cells may fail." (PMID 40667699, 2025).
tumor (continued). "Administration of anti-PD-L1 antibodies to isolated, tumour antigen-experienced CCR7+ BMDC in vitro did not alter their phenotype, but the addition of recombinant IFNγ upregulated expression of OX40L, PVR and CD40, consistent with the activated Ccr7_DC.2 state." (PMID 38267413, 2024). "However, a recent study found the anti-tumor efficacy of neoantigen/toll-like receptor 3 (TLR3)/CD40 agonist vaccine and neoantigen-specific CX3CR1+ CD8+ T cell generation relied on CD40 and CD80/86, rather than the CD70 signaling pathway." (PMID 36263174, 2022). "A drawback of the CD40/TAA approach is its dependence on sufficient expression levels and density of a specific TAA, which may not be uniformly expressed across different tumor lesions and patients." (PMID 35911742, 2022). "Furthermore, CD40 is moderately correlated with BATF3 (dendritic cells) in normal (r = 0.30) and tumor (r = 0.36) tissues." (PMID 34758832, 2021). "Therefore, the positive prognostic value of high CD40 and LAPTM5 expression is attributed to the tumor tissue and not to the immune cells." (PMID 32582531, 2020). "CD40, a member of the TNF receptor family, is broadly expressed on many cell types, including APCs, DCs, B cells, macrophages, monocytes, as well as a number of nonhematopoietic cell types and some tumor cells." (PMID 31805946, 2019). "The experimental data showed that the protein expression of CD40, CD80, CD86, and HLA-DR on CD1c+ DCs was downregulated after co-culture with primary NSCLC cells compared with that on CD1c+ DCs that were not cocultured with tumor cells." (PMID 31921114, 2019). "Compared to CAR-T cells that did not secrete anti-CD40 antibodies, MSLN3-CD40 CAR-T cells secreted increased levels of cytokines in response to target antigen stimulation and enhanced antitumor activity in a xenograft tumor model established by subcutaneous inoculation of 1 × 107 SKOV-3-luc cells." (PMID 39350256, 2024). "Indeed, the combination of HDAC3 inhibitor RGFP966 with a DNA demethylation reagent, 5-aza-2-deoxycytidine, synergistically enhanced the expression of several tumor suppressors such as p16, PTEN, STAT1, CD40, and large non-coding RNA MEG3, accompanied by growth suppression." (PMID 35646715, 2022). "In contrast to previously published findings with other tumor models, we did not observe a significant difference in tumor growth in JAX mice compared to TAC mice of untreated 9464D-GD2 tumors or tumors treated with RT alone or RT and combined 1⁄2 dose IT-IC, anti-CTLA-4, CpG, and anti-CD40." (PMID 31810498, 2019). "This suggests that whilst IL-2/CD40 reduces tumor-induced suppressive TDLN CD11c+ cells, it does not overcome the age-related increase in suppressive CD11c+ cells, which may be a contributing factor to the reduced efficacy of IL-2/CD40 in elderly mice." (PMID 30560130, 2018). "Thus, we hypothesize that CD8+ T cells recognize tumor antigens presented by the cancer cells via MHC-I, whereupon they become activated and express CD40L, which directly triggers noncanonical cytotoxicity in CD40+ cancer cells." (PMID 40397730, 2025).